CTLA4 (cytotoxic T-lymphocyte associated protein 4)
Diseases named in the same sentence as CTLA4 in open-access papers (continued):
Sharing a sentence is not in itself a finding about the gene and the disease.
tumor (continued). "Targeting CTLA-4 with a type of monoclonal antibodies in immunotherapy was a prospective therapeutic approach in many types of tumor by enhancing the activation and expansion of antitumor T cell." (PMID 33819967, 2021). "Combination of CD40 activating antibody and anti-PD-1/CTLA-4 resulted in tumor regression and immunological memory in KPC mice." (PMID 34290984, 2021). "CTLA-4 was associated with CD3+ and CD4+ T cells and PD-1 expression by tumor cells and stroma (considered separately or as one compartment)." (PMID 34830196, 2021). "[177Lu]Lu-DOTA-folate sensitized, however, the tumors to anti-CTLA-4 immunotherapy, which became obvious by reduced tumor growth and, hence, a significantly improved median survival time of mice (> 70 days)." (PMID 33078260, 2021). "EC Shb KO reduced the expression of immune checkpoint genes Ctla4 and PD-L1 (Cd274) in tumor CD45+ cells, suggesting that the observed reduction in the expression of these genes plays a minor role in the observed increase in metastasis." (PMID 34768912, 2021). "We found that there were a few non CTLA-4 collaboration genes upregulated in normal tissue and non-tumor diseased tissue Treg in spleen (23 genes), VAT Treg (10 genes) and kidney Treg (11-16 genes)." (PMID 34084175, 2021). "To date, several clinical trials are ongoing investigating personalized neoantigen-based vaccines alone or in combination with anti-PD-1, -PD-L1 and/or -CTLA-4 antibodies in various tumor types, comprising NSCLC." (PMID 35069581, 2021). "Anti-CTLA4 binds to CTLA4 with higher affinity leading to increased accumulation, function and survival of T cells that attack tumour cells." (PMID 33921181, 2021). "One-way ANOVA analysis showed that the density of CTLA-4+ TILs in tumor tissues from the four subgroups was significantly different (P = .031)." (PMID 34526987, 2021). "The proposed mechanism of action consists of both an indirect effect through inhibition of Treg accumulation in tumor and a direct cytotoxic T lymphocytes action through inhibition of CTLA-4 interaction with B7 ligands." (PMID 36046145, 2021). "•For the Tregs in the primary tumor, there is transcript downregulation of components of the T cell receptor complex and CTLA-4." (PMID 34375938, 2021). "CTLA-4 is a transmembrane protein exclusively expressed on T cells and Tregs in tumor infiltrating lymphocytes (TILs)." (PMID 34959285, 2021). "Immune checkpoint inhibitors therapy, especially those targeting PD-1/PD-L1 and CTLA-4, have showed an efficacy in several tumor types." (PMID 34880206, 2021). "Co-inhibitory CTLA-4 competes with co-stimulatory CD28 to bind to CD80 or CD86 on the surface of APCs to alleviate the anti-tumor immunity of tumor infiltrated T lymphocytes (TILs), such as CD4+T, CD8+T cells and regulatory T cells (Tregs)." (PMID 34858835, 2021). "CTLA-4 positive staining is mainly localized in lymphocytes, the tumor cell membrane, and the hepatocyte cytoplasm in adjacent liver tissues." (PMID 34526987, 2021). "In a lung cancer mouse model, chemotherapy promotes the ICD pathway to enhance the anti-tumor ability of anti-PD-1 and anti-CTLA4 antibodies." (PMID 34201650, 2021). "Studies 36 have shown that in the tumor microenvironment, anti-CTLA-4 stimulates the activation of surrounding T cells by blocking the binding of CTLA-4 on the surface of T cells to the ligand CD80/CD86 on APCs, but does not activate T cells." (PMID 33391454, 2021). "Noticeably, anti-CTLA-4 molecules enable the anti-tumor activity of T cells and reduce inhibitory signals through different mechanisms." (PMID 35083014, 2021). "Combination checkpoint inhibitor therapy with CTLA-4 and PD-1 blockade proposes a concomitant tumor attack through two distinct mechanisms." (PMID 34200997, 2021).
tumor (continued). "Anti-CTLA4 therapy shapes T-cell pool involved in anti-tumor recognition by indiscriminately broadening blood TCR repertoire (which also increase treatment side effects) and by increasing the number of tumor reactive T-cell clones." (PMID 34899700, 2021). "In our study, we showed that CTLA-4 blocking antibodies can also be used to overcome CAF-mediated exclusion of CD8+ T-cells in tumour models." (PMID 34262652, 2021). "In in vivo experiments, when further combined with CTLA-4, the primary and metastasis sites of the tumor were completely inhibited while substantial helper CD4+ and cytotoxic CD8+ T cells infiltrations were detected in the metastatic sites." (PMID 34656118, 2021). "The use of ICIs, by blocking either CTLA4, PD-1, or PD-L1, results in an upregulation of the immune response, which helps target and destroy tumor cells." (PMID 33981507, 2021). "Taken together, our study showed that m6A modification-related patterns were significantly correlated with tumor immune phenotypes and clinical response to anti-CTLA4 therapy." (PMID 34686691, 2021). "CTLA-4 interferes with early T cell activation, and anti-CTLA-4 leads to increased activation and proliferation of T cells in lymphoid organs and tumor tissues." (PMID 34307177, 2021). "In another study, anti-CTLA-4 blockade or Treg cell depletion after RFA or cryoablation increased tumor-specific T cell number and cytokine secretion." (PMID 34575463, 2021). "The well-studied immune checkpoints including CTLA-4, PD-1, and PD-L1 play crucial roles in the tumor immunoreaction process." (PMID 34248623, 2021). "Previously published results demonstrated impairment of secondary tumor growth after primary TRAMP-C2 tumors were destroyed by cryotherapy combined with anti-CTLA-4 treatment." (PMID 34162858, 2021). "CTLA4+ tumor-infiltrating cells have been found to be an independent prognostic factor in OSCC, showing that its high infiltration indicated worse recurrence-free survival and metastasis-free survival." (PMID 35127742, 2021). "The addition of CTLA-4 blockade appeared to limit the enhancement of T cell migration from the peri-tumor region to the core." (PMID 34572844, 2021). "The synergistic antitumor effect of anti-CTLA-4 in our systems relies on the reinvigoration of tumor-reactive CTLs by re-enabling CD28 co-stimulation with DCs." (PMID 34006895, 2021). "Ligands for inhibitory receptors on circulating lymphocytes, such as CTLA-4, PD-1, (PD-L1 is the ligand for PD-1) and T cell immunoglobulin mucin-3 (TIM-3), are overexpressed by HNSCC tumor cells and are associated with worse survival." (PMID 34771432, 2021). "In contrast, the highly immunogenic CT26-HER2 tumor was recognized by the immune system and appeared to actively fight for its survival by adopting several strategies (CTLA-4, LAG3, PD1, and Tregs) that reverse the activity of the antitumor immune effectors." (PMID 34578328, 2021). "One approach to overcome tumor escape is the use of immune checkpoint inhibitors (ICIs) to block the inhibitory factors that hamper the host's immune response, such as CTLA‐4, programmed cell death protein 1 (PD‐1), and its ligand, PD‐L1." (PMID 33252831, 2021). "CT-26 tumor mice were more sensitive to the anti-PD-1 antibody than Colon 26, while both models show similarly sensitivity to anti-CTLA4 antibody." (PMID 34774008, 2021). "In a preclinical model of metastatic PCa, combined irradiation of metastases and anti-CTLA-4 efficiently induced response of T cells and improved both local anti-tumor effects and also distant response, suggesting an abscopal effect." (PMID 34595122, 2021). "Lastly, TAMs found in human renal cell carcinoma tumor can induce CTLA-4 and Foxp3 expression in T lymphocytes in vivo, further emphasizing the critical role of TAMs in cancer-related inflammation, immunosuppression, and malignant progression." (PMID 34771482, 2021).
tumor (continued). "Tumor-free mice that were initially treated with MP-OVA/Riboxxim alone or in combination with anti-CTLA-4 mAb were re-challenged on day 60 post tumor challenge with E.G7 tumor cells at the contralateral side of the primary tumor site." (PMID 34006895, 2021). "As well, these cells’ anti-tumor activity can be potently intensified by simultaneous ablation of PD-1 and CTLA-4." (PMID 34321099, 2021). "Mice that received [177Lu]Lu-DOTA-folate and anti-CTLA-4 immunotherapy (group D), responded in 8 out of 11 cases, demonstrated by decreasing tumor volumes over time, and in 7 cases the NF9006 tumors disappeared entirely." (PMID 33078260, 2021). "This is of pivotal importance, given the involvement of IFN-γ in host–tumor interactions and in mechanisms of tumor resistance to therapeutic CTLA-4 blockade." (PMID 34968251, 2021). "While immune checkpoint inhibitors that target PD-1 and CTLA-4 are leading the charge in clinical efficacy, there are a number of other promising tumor immunotherapies in advanced development such as Listeria-based vaccines." (PMID 33936058, 2021). "On the other hand, the overexpression of PD-1/PD-L1 and CTLA-4 is responsible for the exhaustion of CTLs, which leads to tumor immune evasion finally." (PMID 34094974, 2021). "As one of the most important immunosuppressive receptors, CTLA-4-targeted immune checkpoint inhibitors are also an important and much researchedtopic in tumor immunotherapy." (PMID 34525966, 2021). "Through overexpression of PD-L1 on the cancer cell surface or inducing PD-L1/CTLA-4 expression on immune cells, cancer cells use the PD-1/PD-L1 and CTLA-4 pathway resulting in immune escape and tumor growth." (PMID 33673374, 2021). "Recent studies have highlighted the presence of CD28 and CTLA-4 on the surface of tumor-infiltrating NK cells in several mouse models of solid tumors." (PMID 34572799, 2021). "In murine models, tumor irradiation when combined with an anti-CTLA-4 antibody has demonstrated synergistic systemic antitumor effects and metastasis inhibition." (PMID 34063238, 2021). "Of note, as shown in the spider plot of tumor growth, only some mice displayed response to anti-CTLA-4 treatment, whereas the majority of mice displayed complete response to the combination treatment." (PMID 33707313, 2021). "While PD-L1 levels were usually evaluated by RT-PCR analysis, some authors found that miR-424-3p (analyzed by in situ hybridization) significantly correlated to CTLA-4 (p < 0.001) and PD-L1 (p = 0.040) immunohistochemical expression in tumor cells." (PMID 34830196, 2021). "A classified ‘cold’ neuroblastoma tumor achieved complete tumor eradication upon immune stimulation with anti-CTLA-4, anti-CD40, and toll-like receptor 9 (TLR9) agonist in addition to radiation and anti-GD2-IL-2." (PMID 33803078, 2021). "To this end, we employed IFNGR1−/− mice and adoptive transfer of total IFNGR1−/− T cells to tumor-bearing mice, and found that loss of IFNGR1 in T cells completely abrogated the efficaciousness of combined anti-CTLA-4 and anti-PD-1 therapy." (PMID 34830176, 2021). "Such a combination (anti-PD1/PDL1 and anti-CTLA4) has been shown to be effective in several tumour groups leading to approvals in the first line advanced setting in mesothelioma, renal cell carcinoma, melanoma and non-small cell lung cancer (NSCLC)." (PMID 34640541, 2021). "The preclinical combination of PI3Kγ inhibition and ICI showed promising outcomes: co-administration of PI3Kγ inhibitor with either anti-PD1 or anti-CTLA-4 significantly inhibits 4T1 tumor growth compared with ICI treatment alone." (PMID 34026830, 2021). "Both immune checkpoints are hijacked by cancer cells, which promote CTLA-4 induction in T lymphocytes and induce PD-L1 expression in tumor cells as a mechanism of immune evasion." (PMID 33540543, 2021).
tumor (continued). "The density of positively stained CTLA-4+-infiltrating lymphocytes in the tumor tissue was 22.0 ± 19.1/field, which was significantly higher than in para-tumor hepatic tissue (7.5 ± 7.8/field, P <.001)." (PMID 34526987, 2021). "They further found that mice administered with inosine showed improved anti-tumor effects from anti-CTLA-4 antibody therapy, a benefit that was dependent on A2AR signaling specifically in T cells." (PMID 34162429, 2021). "When co-cultured with either 90Y-NM600-treated MOC2 or 90Y-NM600-treated B16 cells, both CD4+ T cells and CD8+ T cells demonstrated significantly increased expression of CTLA-4, as compared to those co-cultured with untreated control tumor cells." (PMID 33995649, 2021). "In fact, this Nb-based CTLA-4 blocking strategy achieved an anti-tumor efficacy close to that of monoclonal antibodies." (PMID 34525966, 2021). "Considering the vital role of immune checkpoint molecules (PD-1, PD-L1, LAG3 and CTLA-4) in tumor immune microenvironment, we analyzed the expression of these molecules in two TNF patterns." (PMID 34691075, 2021). "Dual blockade of ICOS with anti-CTLA-4 has been effective in eliciting anti-tumor responses in ICOS knockout mice that were unresponsive to anti-CTLA-4 monotherapy." (PMID 34025438, 2021). "As shown in our data, the Cluster 2 pattern was significantly related to increased levels of tumor-infiltrating monocytes and CTLA-4, supporting the potential predictive value of immunotherapy for HP-induced GC." (PMID 35004676, 2021). "In conclusion, anti-CTLA-4 indirectly influenced NK cell activity, possibly through the (relative) reduction of Tregs and tumor load." (PMID 33572396, 2021). "Critically DTP reduced CD103+ dendritic cell (DC) populations in the tumor microenvironment which accounted for resistance to combination anti-CTLA-4 and anti-PD1 antibodies after progression of the targeted therapy triplet." (PMID 34944961, 2021). "Anti-CTLA-4 treatment can remove the inhibitory effect of T cells, thus supporting the anti-tumor immune response." (PMID 34630121, 2021). "While PD-1 pathway inhibition has a more tumor-specific therapeutic effect, and typically fewer side effects compared to CTLA-4 based therapies, there is still a need to improve the implementation of checkpoint inhibition strategies." (PMID 34136405, 2021). "One of the most successful types of immunotherapy is the immune checkpoint inhibitors, such as anti-CTLA-4 and anti-PD-1, that keep anti-tumour T cells active." (PMID 33262520, 2021). "Together, this improved T-cell proliferation and the cytotoxic potential of CD8+ T-cells in the tumour, and allowed evofosfamide, in combination with CTLA-4/PD-1 blockade, to cure most animals bearing TRAMP-C2 tumours (82% overall survival)." (PMID 33923305, 2021). "The induction of Tregs within the TME, however, dampens antitumor immunity, allowing the tumor to grow uninhibited through expression of various immune checkpoint molecules including CTLA-4, PD-1, LAG-3 and TIM-3." (PMID 33800156, 2021). "Collectively, these observations highlight the importance of a systemic immune reinvigoration in the mediation of anti-CTLA-4 action on the tumor." (PMID 33602280, 2021). "Our results showed that CTLA4 expression is related to the tumor infiltration characteristics of multiple immune cell types." (PMID 34712271, 2021). "While Tregs are regarded as suppressive regulators in tumor immunology and a biomarker of poor prognosis, they still possess specific reactivity against tumor antigens, facilitating CTLA-4 therapy." (PMID 34620200, 2021). "In the future, the model can be expanded by considering the interactions between immune cells and tumor cells, such as the regulatory role of checkpoint proteins (e.g., CTLA-4 and PD-1) on T cell activation." (PMID 35186943, 2021).
tumor (continued). "The treatment with Anti-CTLA-4 antibodies (Ipilimumab) was the first among treatments with immunological blockers to inhibit the action of CTLA-4 in the immune tolerance to tumor cells." (PMID 34062708, 2021). "ICIs target negative costimulation receptors or their ligands of TCR signals, such as CTLA4, PD-1 and PD-L1, to prevent tumor cells attenuate T-cell activation." (PMID 35095898, 2021). "In order to assess which T cell subsets were the main target of CTLA-4 blockade in the tumor microenvironment, we next evaluated the level of CTLA-4 expression on T cells." (PMID 33923750, 2021). "CTLA4 hypomethylation thus appears to be a robust surrogate biomarker for an enriched tumor microenvironment." (PMID 34446578, 2021). "We furthermore showed that combined treatment with anti-PD-1 and anti-CTLA-4 mAbs significantly delays tumor development and even gives rise to long-time survivors, while therapy with single mAbs remains uneffective." (PMID 33141285, 2021). "Responses yielded by RT+L19–IL2 and RT+L19–IL2+anti-CTLA-4 were comparable between the three tumor models." (PMID 33688020, 2021). "The apparent uncoupling of the dynamics of the peripheral TCR repertoire with tumor response therefore questions the role of the T cell reinvigoration induced by CTLA-4 blockade in the periphery in leveraging the anti-tumoral action of the treatment." (PMID 33602280, 2021). "Originally, adjuvant anti-CTLA-4 therapy following surgery was shown to be an effective therapeutic approach for targeting residual tumor cells in studies of transgenic mice." (PMID 33820953, 2021). "To this end, we performed parabiosis surgery on tumor-free animals that had undergone therapy with either surgical tumor resection or IRE ablation to remove the tumor mass, followed in both cases by treatment with anti-CTLA-4." (PMID 34162858, 2021). "As immune checkpoints are not limited to PD-L1 and CTLA4, they can reflect the immunosuppressive condition of the tumor environment and can predict ICI efficacy to a certain extent." (PMID 33833986, 2021). "The interaction between CTLA-4 mAbs and the activating Fc receptors is critical for selective depletion of Tregs in the tumor." (PMID 34806028, 2021). "As such, in this paper, we describe an in situ crosslinked hydrogel for the sustained release of antibodies blocking CTLA-4 and PD-1 signaling from a locoregional injection proximal to the tumor site." (PMID 33673289, 2021). "Taken together, these observations implicate CTLA-4 during the priming phase, the first step of immune system activation against tumor and infection." (PMID 34572799, 2021). "For paired tumor tissues, the percentage of intratumoral CTLA4 was higher in oligometastatic lesions than primary tumor (P=0.043)." (PMID 34858823, 2021). "This paradigm was proven in mice; for example, a study demonstrating that three fractions of eight Gy had a better response than five fractions of six Gy in inducing anti-tumor immunity in combination with anti-CTLA-4 antibodies." (PMID 34199805, 2021). "High CTLA-4 epithelial expression showed a significant relationship with an infiltrative TBC (p = 0.001) which is explained as CTLA-4 expression correlates with invasive tumour power." (PMID 35047074, 2021). "Subsequently, we examined the effect of immune checkpoint inhibitors targeting CTLA-4 and the PD-1/PD-L1 axis to further enhance the anti-tumor response using MCF-7 tumor spheroids." (PMID 34484225, 2021). "In preclinical studies, the blockade of CTLA-4 led to a 1.5–2-fold increase in T-cell proliferation, enhanced IL-2 production, and depleted Treg in the tumor microenvironment." (PMID 34359588, 2021). "A significant decrease in tumor growth and significant increase in tumor-free survival were observed in mice that received both anti-CTLA-4 and rapamycin during T cell priming compared to either treatment alone." (PMID 33802831, 2021).